UBE2CP1 (ubiquitin conjugating enzyme E2 C pseudogene 1)
Gene: Processed pseudogene on chromosome 14 (30,683,045 to 30,683,598, reverse strand). Ensembl gene ENSG00000258648.
Diseases named in the same sentence as UBE2CP1 in open-access papers:
UBE2CP1 is named in the same sentence as 1 disease in open-access papers, as found by Europe PMC text mining. Sharing a sentence is not in itself a finding about the gene and the disease.
UBE2CP1 shares sentences with these, for which no sentence is quoted: gastric cancer (1 paper).